NME1-NME2 (NME1-NME2 readthrough)
Synonyms: NM23-LV; NMELV
Gene: Protein-coding gene on chromosome 17 (51,153,590 to 51,171,744, forward strand). Ensembl gene ENSG00000011052.
Genetic constraint (gnomAD): Loss-of-function variants: 27 observed, 32.47 expected, observed/expected ratio (o/e) 0.83, 90% interval 0.61 to 1.15. The upper end of that interval is the gene's LOEUF score, 1.15, which puts it in group 5 of 6, group 1 being the genes least tolerant of losing a copy. Missense variants: 286 observed, 366.67 expected, observed/expected ratio (o/e) 0.78, 90% interval 0.71 to 0.86. Synonymous variants: 125 observed, 131.17 expected, observed/expected ratio (o/e) 0.95, 90% interval 0.82 to 1.11.